IGF1R (insulin like growth factor 1 receptor)
Diseases named in the same sentence as IGF1R in open-access papers (continued):
Sharing a sentence is not in itself a finding about the gene and the disease.
tumor (continued). "In addition, miR-NC transfected HBMSCs decreased the expression levels of IGF1R in tumor tissues compared with that in PBS group (p < 0.05), and miR-99b-5p mimics transfected HBMSCs further reduced the expression levels of IGF1R compared with miR-NC transfected HBMSCs (p < 0.05)." (PMID 35030978, 2022). "Other studies revealed that IGF-1 that is bound to IGF-1R may stimulate mitosis and cell migration, prevent apoptosis (via the activation of MAPK and PI3K signalling pathways) as well as enhance tumour angiogenesis via raising vascular endothelial growth factor levels." (PMID 35328822, 2022). "Comparison of normal and tumor tissue at long-term culture showed increased expression of IGF1R (5-fold, p < 0.0001) and IGFBP6 (3.5-fold, p < 0.01), whereas IGFBP1 (4-fold, p < 0.05), IGFBP3 (2.5-fold, p < 0.01) and IGFBP4 (4-fold, p < 0.01) were downregulated in tumor slices." (PMID 35884847, 2022). "Insulin resistance-induced alterations in the composition of the IGF family (comprising IGF-1, IGF-2, their receptors, IGF-1R and IGF-2R, and six types of IGF binding proteins (IGFBPs), IGFBP-1 to 6, have been demonstrated to be of key importance in the formation and progression of tumours." (PMID 35328822, 2022). "By analysing those clinical data from medicine trials, we found that blocking bioactivity of IGF1R or IGF ligands using antibody was not appropriate because antibodies could not eliminate the overexpression of IGF on the surface of tumour cells." (PMID 33621401, 2022). "Importantly, in our in vivo models, we have shown that N157 treatment reduces UM tumor growth, indicating that targeting IGF-1/IGF-1R signaling could be a potential therapeutic strategy." (PMID 36551732, 2022). "However, most anti-tumor IGF-1R mAbs or TKIs have not yet displayed significant benefits in patients randomly recruited to phase II/III clinical trials, which is probably due to the paucity of reliable predictive biomarkers of IGF-1R inhibition." (PMID 36233084, 2022). "Further supporting the complexity of crosstalk between IGF-1R and other tyrosine kinase receptor pathways, unclear synergistic actions of EGF, PDGF, TGF-β, and IGF induce stemness, cancer progression and metastasis, drug resistance, and tumor relapse in various cancer types." (PMID 36017326, 2022). "In addition, to determine how the lack of IGF1R in the lung TME is conditioning tumor growth and metastasis, we performed double fluorescence immunostainings of p-IGF1R with CD68 (TAMs) and FOXP3 (FOXP3+ TILs) in lung sections from LLC-challenged mice." (PMID 35688943, 2022). "Human tumor transcriptomic data for 377 HCC patients also show a positive correlation of multiple ABC transporters including the ABCB1, ABCC3, ABCC9 and ABCG2 with GHR expression, while ABCC1,ABCC4 and ABCG1 levels correlated with IGF1R expression, confirming our in vivo observations." (PMID 35865483, 2022). "Our data show that MMP-9, a matrix metallopeptidase previously shown to be involved in tumor vascularization and metastasis is decreased eightfold in the presence of SSO55 and reduced to near undetectable levels in the presence of both SSO55 and IGF-1R-blocking antibody." (PMID 35017650, 2022). "Notably, although IGF1R degradation was evident in implanted tumours, the PROTABs were well tolerated and no measurable IGF1R degradation was observed in the normal colonic mucosa." (PMID 36131013, 2022). "In addition, IGF-1R has a synergistic effect on ALK signaling due to its protein Insulin receptor substrate 1 (IRS-1) which inhibits the IGF1R/IRS1 pathway and increases the sensibility of the tumor cells to ALK targeting." (PMID 34082691, 2022). "However, systemic IGF-1 treatment did not alter tumor development in the mice injected with the naturally occurring densities of IGF-1R fibroblasts; this effect was dependent on the dose and the IGF-1R expression level." (PMID 35203722, 2022).
tumor (continued). "The blood–brain barrier permeable small molecule inhibitor of IGF-1-R, picropodophyllin (PPP), shows promising antitumoral effects in treatment of gliomas and could be used for another way of disrupting paracrine neuron-tumor signaling." (PMID 36357661, 2022). "Among them, the insulin-like growth factor 1 receptor/insulin receptor substrate 1 (IGF1R/IRS1) signaling pathway contributes to the transformation and growth of malignant cells, and enhances the migration and invasiveness of tumor cells in several types of cancers, including OC7–10." (PMID 33723215, 2021). "As the tumor grows, there is a reduction in oxygen at the center of the tumor, creating adverse conditions of hypoxia, which induces increased expression of numerous pro-angiogenic factors, such as hypoxia-inducible factor 1-alpha (HIF-1α) and insulin-like growth factor type 1 receptor (IGF-1R)." (PMID 33419057, 2021). "TKIs’ lack of selectivity might have some benefit—upregulated serum levels of insulin after IGF-1R monoclonal antibody treatment may not have as much effect on the tumor if both IGF-I1 and IR are blocked." (PMID 33829018, 2021). "Targeting isoforms p110β and p110δ via RNAi could reduce AKT activation through IGF-I or insulin, indicating that both PI3K isoforms contributing to the upregulation of IGF-1R or IR in AML cells and improving the sensitivity of tumor cells to chemotherapeutical drugs." (PMID 33768092, 2021). "Insulin and its analogues may function as growth factors and therefore have a theoretical potential to promote tumor proliferation through various mechanisms involving activation of the insulin receptor, IGF-1 receptor (IGF-1R) and extracellular-signaling-regulated kinase (ERK) pathways." (PMID 34535145, 2021). "IGF-1R knockdown via NVP-AEW541, 3-MA, and Atg7 siRNA could induce TNBC cell-protective autophagy and thereby attenuating the efficacy of IGF-1R-modulating therapeutic agents in tumor cells." (PMID 33768092, 2021). "We also reported that nuclear IGF-1R undergoes ligand-induced recruitment to regulatory regions of chromatin, and interacts with RNA Polymerase II (RNAPolII) to promote RNAPolII recruitment and expression of genes including JUN that drive tumour cell proliferation and migration." (PMID 33969359, 2021). "Downregulation of IGFBP-6 or IGF-I or IGF-II expression levels via siRNAs in breast epithelial cells or knockdown IGF-1R activity on fibroblasts could play an effective role in changing fibroblast mobilization, suppressing TME remodeling and tumor invasion via the IGFs/IGF-1R axis." (PMID 33768092, 2021). "Emphasizing the importance of modeling the tumor environment, Santoro and co-workers showed that culture of EwS cells on 3D scaffolds within a flow perfusion bioreactor promoted insulin-like growth factor-1 (IGF1) production and revealed shear stress-dependent resistance to an IGF-1R inhibitor." (PMID 33919988, 2021). "Notably, IGF2BP3 sustained IGF2 and IGF1R mRNA translation in tumor cells but any involvement of the IGF2BP3/IGF2/IGF1R axis in response to BET inhibitors has not been yet established." (PMID 34440844, 2021). "However, not all T-ALL cell lines are sensitive to IGF1R inhibition, with co-expression of surface IGF1R and tumor-suppressor PTEN indicating IGF1 dependence." (PMID 34394130, 2021). "This suggests that binding to IGF‐1R alone is not sufficient for a good antitumor response and that in tumor cells the PI3K/MAPK pathway may remain activated, possibly also through InsR." (PMID 31490549, 2020). "Nearly 75% of the baseline tissues analyzed had absent or 0–<33% tumor expression of IGF-1R." (PMID 32976223, 2020). "In addition to the formation of heterodimers within the HER-family there is also a cross talk between EGFR and other receptor tyrosine kinases such as the insulin like growth factor 1 receptor (IGF-1R), which is also involved in tumor development and progression." (PMID 32903756, 2020).
tumor (continued). "Tumor cells lacking cytoplasmic IGF1R immunostaining (cCC-IGF1R 0) were found in 927 (61.8%) cases." (PMID 32727431, 2020). "However, even though the IGF-1R targeting antibodies AMG-479, IMC-A12 (cixutumumab) and TKI NVP-AEW541 have been shown to reduce tumor proliferation in pancreatic, breast cancer and endometrial cancer cells in preclinical models, they are likely ineffective as monotherapies." (PMID 32825010, 2020). "On the other way around, our pharmacological and RNAi experiments demonstrated that even saturated amount of PDGFAA could not support tumor OPCs to growth without the proper function of IGF1R." (PMID 33173731, 2020). "Finally, the use of the off-target IGF1R inhibitor ceritinib may accelerate the development of clinical protocols for the treatment of tumor entities driven by IGF2 and IGF1R." (PMID 31234291, 2019). "IGF1R is not the main driver of tumor development but is required for transformation and growth." (PMID 30979001, 2019). "Therefore, a dual inhibitor of both kinases may selectively block tumor growth, migration and survival of FAK- and IGF-1R-expressing tumor cells compared to proliferating and migrating normal cells." (PMID 31215459, 2019). "IGF-1R expression in tumor tissue before and after neoadjuvant treatment did not predict survival." (PMID 31455425, 2019). "Although IGF1R was not expressed in the tumor, IGF2R was overexpressed." (PMID 30168002, 2018). "The mechanisms by which decreased IGF-1R function might contribute to an aggressive, invasive tumor phenotype have not been identified." (PMID 30458886, 2018). "We did not have access to tumor tissue after tamoxifen exposure and could, therefore, not examine whether there was a differential tamoxifen response with respect to ER and IGF1R levels between normal-weight patients and those with higher BMI." (PMID 29928262, 2018). "IGF1R has been reported in multiple studies as a key mediator of bypass-resistance to HER2 inhibition;20–22 the top ranking of IGF1R thus validates the capacity of our screening approach to uncover bona fide regulators of tumor cell responsiveness to lapatinib." (PMID 30323337, 2018). "The tumor cells were positive for IGF2R but negative for IGF1R." (PMID 30168002, 2018). "As alluded to above, fusion of EWSR1 to WT1 in this pediatric malignancy abrogates the tumor suppressor role of WT1 as well as the RNA-binding capacity of EWSR1, and generates an oncogenic molecule capable of binding and transactivating WT1 target genes, including the IGF1R promoter." (PMID 29455671, 2018). "However, no data regarding tumor-specific IGF1R levels in the breast cancer patients were available at the time of that study." (PMID 29928262, 2018). "IGF1R was also frequently expressed in tumour samples from patients with nonseminomas." (PMID 29160922, 2018). "Moreover, mRNA expression in the tumor of patient #17 (validation set) was increased by 14‐fold compared with the median of tumors without IGF1R amplification." (PMID 27891760, 2017). "Therefore, although being effective in targeting tumor phenotypes in proliferating cells, these two drugs would further decrease the effectiveness of already lowered levels of IGF1R and VEGF, thereby exacerbating the undifferentiated phenotype and the aggressiveness of tumor cells." (PMID 29152063, 2017). "The levels of mRNA expression in the tumor of patient #4 (discovery set) was increased by 69‐fold compared with that in the adjacent normal tissues and by 33‐fold compared with the median in tumors without IGF1R amplification." (PMID 27891760, 2017). "The reduced expression of IGF-1R and VEGF may help prevent the development of tumors by reducing the insulin-like growth factor-1 (IGF-1)-mediated cell survival and proliferation pathways and preventing tumor-induced angiogenesis." (PMID 28300758, 2017).
tumor (continued). "For InsRmod/high in all patients, the results became significant HRadj 0.60 (95%CI 0.37-0.97), while for IGF1Rstrong the subgroup of AI-treated patients >50 years old with ER+ tumors, the results became non-significant when using the IGF1R status for the contralateral tumor." (PMID 28030849, 2017). "In addition, H1047R mouse tumor cells, RDR‐C234 and RDR‐A677, derived from recurrent tumors, responded more efficiently to a combination of inhibitors of PI3K (both LY294002 and GDC‐0941) and IGF‐1R (OSI‐906) in comparison with single treatments." (PMID 28296140, 2017). "A combination of BYL719 with IGF1R (AEW541) or p110β inhibitors (GSK2636771 was used as a p110β inhibitor instead of AZD6482 to ensure better tolerability in combination) strongly decreased tumor growth whereas either agent alone did not." (PMID 27048245, 2016). "Using our approach, we could not investigate the best responders (MP5) after chemotherapy because inherently no tumor tissue was left to measure IGF-1R in the operation specimen." (PMID 26738606, 2016). "Moreover, we show that each of four patients with matched cell lines and primary tumours had strong membranous IGF1R expression in the cultured cells compared to absent or very weak expression in the corresponding primary tumour." (PMID 27418340, 2016). "Even though both CP and metformin target IGF-1R signaling pathway, the combination might further inhibit IGF-1R activation, and/or either metformin or CP have additional anti-tumor effects that are not overlapped with each other." (PMID 27488947, 2016). "Inhibitors of signaling specific to reciprocally engaged tumor cells, such as or AKT or IGF1R/AXL, block heterocellular phenotypes (e.g., protein expression, proliferation, mitochondrial performance, and anti-apoptosis), but have little effect on KRASG12D tumor cells alone." (PMID 27087446, 2016). "Here, we show that this is restricted to tumours expressing high levels of IGF1R, IGF2R or HER2, whereas no prognostic significance could be seen in the IGFR/HER2 negative group." (PMID 26698305, 2015). "Whether IGF-1R contributes to EMT or to non-invasive tumor growth may be strongly influenced by the degree of extracellular matrix engagement and the presence or absence of key proteins in IGF-1R-cell adhesion complexes." (PMID 26191041, 2015). "Nevertheless, the response to therapy targeting IGF1R was relatively low due to the lack of predictive tumor biomarkers that could assist in selecting patients who would benefit from the proposed treatment." (PMID 24904527, 2014). "Furthermore, mTOR inhibitors induce Akt activation through an IGF-1R-dependent negative feedback loop in different types of human cancer cell lines, which weakens the anti-tumor effect of mTOR inhibitors." (PMID 25026290, 2014). "IGF-1R is a receptor tyrosine kinase (RTK) that stimulates protein synthesis by activating the mammalian target of rapamycin (mTOR), and in turn mTOR mediated upregulation of glycolytic enzymes may promote tumor development." (PMID 25048361, 2014). "One patient, who achieved a partial remission (PR) with IGF1R inhibitor treatment, but later developed resistance, demonstrated a KRAS mutation in the post-treatment resistant tumor, but not in the pre-treatment tumor suggesting that the RAF/RAS/MEK pathway was activated with progression." (PMID 25119929, 2014). "However, it is reported that overexpression of IGF-1R in a mouse model of transgenic expression of a constitutively active IGF-1R induces tumor development without the stimulation by any exogenous IGF-1R agonists or estrogen." (PMID 22720981, 2012).
tumor (continued). "In animal models, lack of IGF-1R did not prevent tumor formation or progression when c-myc was induced and ectopic expression of c-Myc could override the suppressive effects of p16, p21 and p27 to promote cell cycle progression." (PMID 21423728, 2011). "Since there are no known activating mutations for IGF1R, we generated a constitutively activated chimeric receptor that is capable of transforming NIH-3T3 cells into a rapidly growing xenograft flank tumor model that is shown to be exquisitely dependent upon IGF signal transduction." (PMID 19732452, 2009). "Consequently, the tumor weights were not measured at the same time, which might explain why the change in tumor weights in the IGF1R inhibitor group and combined group were not significantly different compared to the control." (PMID 39450263, 2024). "Furthermore, our study demonstrates that the IGF1R inhibitor linsitinib, known for its reported inhibition of tumor growth in various cancers, did not augment the inhibitory effect on tumor growth in Igf2-cKO mice and mice with specific fibroblast depletion (iDTRfl/flS100a4CreERT mice)." (PMID 39545420, 2024). "Therefore, IGF-1R could be a potential biomarker of the drug response and clinical progression in NSCLC patients, as it was demonstrated to act as a promoter of metastasis and tumor progression in the lung tumor microenvironment." (PMID 36902237, 2023). "Dual knockdown of FAK and IGF-1R via TAE 226 and siRNA could lead to remarkable suppression of cell viability, reducing ERK and AKT phosphorylation levels, and promoting apoptosis in PC cells which in turn resulting in caspase-3 activation as well as ADP-ribose and PARP cleavage in tumor cells." (PMID 33768092, 2021). "Furthermore, differentiated tumor cells can dedifferentiate into CSCs by being cocultured with CAFs, which suggests signaling crosstalk between CSCs and CAFs; indeed, a paracrine network of IGF/IGF-1R was found to contribute to cancer stemness in the niche environment." (PMID 31505803, 2019). "The lack of mutations found in IGF proteins in cancer may hint that INSR/IGF1R signalling is not a key driver in many tumours, and together with cross talk between pathways, this could explain the lack of efficacy seen in clinical trials using several different types of IGF1R‐targeted agent." (PMID 31179642, 2019). "In addition, the tumor expressed IGF2 receptor (IGF2R) but not IGF1R." (PMID 30168002, 2018). "Though, multivariable analysis suggested that the reduced recurrence-risk among normal-weight tamoxifen-treated patients with ER+ tumors with known IGF1R tumor expression (n = 254) could not be explained by decreased IGF1R tumor expression (adjusted Ptrend = 0.97)." (PMID 29928262, 2018). "This small leucine-rich proteoglycan may inhibit tumor cell growth, migration, angiogenesis and metastasis by interaction with different receptor tyrosine kinases such as EGF, other erbB family members, c-Met and IGF-1R and upregulation of p21WAF1/CIP1 (p21) via a p-53 independent pathway." (PMID 26437222, 2015). "However, whether IGF-1r can modulate ESCC tumor sensitivity to chemotherapy or radiation therapy, has not been reported." (PMID 25363593, 2014). "In addition to the challenges associated with the development of most inhibitors, including specific tumor delivery and dose-related issues, the large homology that exists between this receptor and the related INSR should be taken into account while developing IGF1R inhibitors." (PMID 24434591, 2014). "Therefore, whether IGF-1R targeted therapy has failed to provide significant response rates due to a lack of intended biologic activity against the tumor remains unknown." (PMID 23761859, 2013). "Moreover, HAA could be useful in further detailing whether a tumour is IGF1-R positive or negative HAA appears to be a useful method for the detection of growth factor receptors, specially in small biopsy specimens." (PMID 1323990, 1992).